TNFRSF19 (TNF receptor superfamily member 19)
Description:
Can mediate activation of JNK and NF-kappa-B. May promote caspase-independent cell death.
Synonyms: TAJ; TROY; TAJ-alpha; TRADE
Tractability: Antibody: UniProt predicts a signal peptide or a membrane-spanning region; its Gene Ontology location is reachable by antibodies, with medium confidence.
Gene: Protein-coding gene on chromosome 13 (23,570,370 to 23,676,104, forward strand). Ensembl gene ENSG00000127863.
Subcellular location: Membrane
Subcellular location (Human Protein Atlas): Golgi apparatus; Nucleoplasm
Gene Ontology:
Molecular function: protein binding; transmembrane signaling receptor activity; tumor necrosis factor receptor activity; signaling receptor activity
Biological process: apoptotic process; cytokine-mediated signaling pathway; JNK cascade; positive regulation of canonical NF-kappaB signal transduction; positive regulation of JNK cascade; tumor necrosis factor-mediated signaling pathway
Cellular component: membrane; plasma membrane
Genetic constraint (gnomAD): Loss-of-function variants: 24 observed, 39.31 expected, observed/expected ratio (o/e) 0.61, 90% interval 0.44 to 0.86. The upper end of that interval is the gene's LOEUF score, 0.86, which puts it in group 3 of 6, group 1 being the genes least tolerant of losing a copy. Missense variants: 470 observed, 508.07 expected, observed/expected ratio (o/e) 0.93, 90% interval 0.86 to 1. Synonymous variants: 188 observed, 196.35 expected, observed/expected ratio (o/e) 0.96, 90% interval 0.85 to 1.08.
Homologues: Orthologues: chimpanzee TNFRSF19 (99% identical), macaque TNFRSF19 (92% identical), dog TNFRSF19 (79% identical), rabbit TNFRSF19 (77% identical), guinea pig TNFRSF19 (74% identical), rat Tnfrsf19 (73% identical), mouse Tnfrsf19 (71% identical), pig TNFRSF19 (66% identical), tropical clawed frog tnfrsf19 (55% identical), zebrafish tnfrsf19 (42% identical). Paralogues in human: EDA2R (23% identical), EDAR (22% identical).
Diseases named in the same sentence as TNFRSF19 in open-access papers:
TNFRSF19 is named in the same sentence as 38 diseases in open-access papers, as found by Europe PMC text mining. Sharing a sentence is not in itself a finding about the gene and the disease. The quoted sentences say what the papers report.
glioblastoma (11 papers, 2019 to 2024). The most malignant astrocytic tumor (WHO grade IV). "TNFRSF19 may be involved in beta-catenin regulation of NF-κB and has primarily been associated with melanoma, glioblastoma, and colorectal cancer." (PMID 35432372, 2022). "Prior research has also demonstrated the significance of TNFRSF19 in promoting glioblastoma cell invasion and resistance to therapy." (PMID 38560169, 2024). "TNFRSF19 is overexpressed in glioblastoma correlating with tumor grade, in myeloproliferative neoplasms, melanoma, lung cancer, and nasopharyngeal carcinoma where it is required for cell proliferation." (PMID 37686244, 2023). "High expression of TNFRSF19 is related to the inferior prognosis in melanoma, glioblastoma, and colorectal cancers, and is reported promoting tumorigenesis via TGFβ signaling pathways in nasopharyngeal carcinoma." (PMID 32719746, 2020). "TNFRSF19, also known as TROY, was inversely correlated with patient survival and could stimulate glioblastoma cell migration and invasion." (PMID 34537809, 2021).
glioma (9 papers, 2012 to 2024). A benign or malignant brain and spinal cord tumor that arises from glial cells (astrocytes, oligodendrocytes, ependymal cells). "In gliomas, higher TNFRSF19 expression is associated with increased numbers of plasmacytoid dendritic cells (DCs) and Th2 cells (P < 0.05)." (PMID 38560169, 2024). "TNFRSF19 expression in GBM is positively associated with glioma grade and inversely related to clinical outcomes." (PMID 38560169, 2024). "Further research is necessary to investigate the potential impact of TFMs on prognosis prediction and to elucidate the function and potential therapeutic targets linked to TNFRSF19 expression in gliomas." (PMID 38560169, 2024). "Given the upregulation of TNFRSF19 in gliomas, we further demonstrated a positive association between TNFRSF19 expression and seven drugs." (PMID 38560169, 2024). "IDH1 mutations were found in 82% of gliomas with low TNFRSF19 expression and 38% of gliomas with high TNFRSF19 expression." (PMID 38560169, 2024). "Kaplan-Meier survival analysis demonstrated a strong association between elevated TNFRSF19 levels and unfavorable clinical outcomes in gliomas across all three cohorts (log-Rank test P < 0.05), consistent with findings from the internal cohort utilizing IHC (log-Rank test P < 0.05)." (PMID 38560169, 2024). "In general, TNFRSF19 demonstrates promise as a target for treatment and a predictor for immunotherapy outcomes in individuals with glioma." (PMID 38560169, 2024). "Endothelial cells and fibroblasts in four cohorts were evaluated using the MCP-counter and ssGSEA techniques.Gliomas exhibiting elevated TNFRSF19 levels showed a higher presence of fibroblasts compared to those with lower levels (P < 0.05)." (PMID 38560169, 2024). "We examined the mRNA expression levels of 37 immune checkpoint genes, specifically PD-L1 and PD-1, in gliomas across four cohorts with varying levels of TNFRSF19 expression." (PMID 38560169, 2024). "There was a significant difference in immune and stromal scores between glioma cases with low and high TNFRSF19 expression levels, with higher scores seen in individuals with high TNFRSF19 expression across all four cohorts (P < 0.001)." (PMID 38560169, 2024). "Functional annotation, immune scores, stromal scores, and genomic alteration patterns were compared between glioma samples exhibiting low and high TNFRSF19 expression." (PMID 38560169, 2024). "The study investigated the expression profile of TNFRSF19 in 12 fresh normal and 124 glioma tissues using IHC." (PMID 38560169, 2024). "As compared to normal tissues and peritumoral tissues, TNFRSF19 was significantly increased in gliomas (P < 0.05)." (PMID 38560169, 2024). "The research we conducted showed a significant link between elevated TNFRSF19 levels in gliomas and a higher number of fibroblasts when compared to gliomas with lower TNFRSF19 levels (P < 0.05)." (PMID 38560169, 2024). "TNFRSF19 exhibited significant upregulation in glioma tissues within the TCGA and Rembrandt cohorts (P < 0.05)." (PMID 38560169, 2024). "In the TCGA cohort, gliomas exhibiting elevated TNFRSF19 expression demonstrated a significantly higher TMB compared to gliomas with low TNFRSF19 expression, with statistical significance (P < 0.05)." (PMID 38560169, 2024). "Gliomas exhibiting elevated TNFRSF19 expression were found to be correlated with heightened levels of immunosuppressive cells across various cohorts, with the exception of CD56dim NK cells (P < 0.05)." (PMID 38560169, 2024). "Increased expression of TNFRSF19 was significantly associated with high-grade gliomas, suggesting a correlation between TNFRSF19 expression levels and glioma invasiveness." (PMID 38560169, 2024).
glioma (continued). "TNFRSF19 played a role in reshaping the immunosuppressive microenvironment in gliomas, and multiple drug-targeted TNFRSF19 molecules were identified." (PMID 38560169, 2024). "This prognostic disparity was further confirmed in our own cohort (P < 0.05), suggesting a potential pivotal role of TNFRSF19 in gliomas." (PMID 38560169, 2024). "TNFRSF19 is an outstanding representative of a predictor of prognosis and immunotherapy effect in gliomas." (PMID 38560169, 2024). "Depletion of Pyk2 inhibits tumor necrosis factor receptor superfamily member 19 (TNFRSF19/TROY)‐mediated glioma cell migration by suppressing TROY‐induced Rac1 activity." (PMID 31368612, 2019). "Previous research has indicated that TNFRSF19 enhances glioma cell survival by activating NF-kB." (PMID 38560169, 2024). "TNFRSF19 emerges as a notable candidate with potential significance in the pathogenesis of gliomas." (PMID 38560169, 2024). "In summary, the dysregulated expression of TNFRSF19 may play a role in shaping the immunosuppressive microenvironment within gliomas." (PMID 38560169, 2024). "Additionally, waterfall plots were utilized to visually represent the genomic alteration patterns in gliomas with differing levels of TNFRSF19 expression." (PMID 38560169, 2024). "Significant differences were observed in the occurrence of plasmacytoid DCs and Th2 cells in gliomas with varying levels of TNFRSF19 expression, with higher levels found in tumors with increased TNFRSF19 expression compared to those with decreased TNFRSF19 expression (P < 0.05)." (PMID 38560169, 2024). "Furthermore, TNFRSF19 exhibited elevated expression levels in glioma tissues compared to peritumoral tissues (P < 0.05)." (PMID 38560169, 2024). "In addition, the TCGA cohort showed that gliomas with high TNFRSF19 levels had higher amounts of 28 immune checkpoint proteins, such as PD-L1, and lower levels of six immune checkpoint genes compared to those with low TNFRSF14 levels (P < 0.05)." (PMID 38560169, 2024). "The results indicate that the uncontrolled TNFRSF19 expression could potentially influence the immunosuppressive environment in gliomas." (PMID 38560169, 2024). "Within the TCGA group, gliomas showing high TNFRSF19 levels exhibited notably increased expression of 28 immune checkpoint proteins, such as PD-L1, and reduced expression of six immune checkpoint genes when compared to those with low TNFRSF19 levels (P < 0.05)." (PMID 38560169, 2024). "One TNFR in particular, TNFRSF19/TROY (Tumor Necrosis Factor Receptor of mouse embryo), has been recently reported to be over expressed in glioma and regulates migration of glioma cells through integrin signaling pathways." (PMID 22649568, 2012). "The findings of our research indicate a significant upregulation of TNFRSF19 in glioma tissues as compared to non-tumor tissues across three cohorts, a result that was further validated in an external set through immunohistochemical analysis (P < 0.05)." (PMID 38560169, 2024).
colorectal cancer (8 papers, 2014 to 2024). A primary or metastatic malignant neoplasm that affects the colon or rectum. "TNFRSF19 exhibits tissue-specific expression, with aberrantly elevated levels reported in various invasive cancers including colorectal cancer, lung cancer, melanoma, and GBM." (PMID 38560169, 2024). "TNFRSF19 has been reported to have a function of an oncogene in nasopharyngeal carcinoma and colorectal cancers cells, but little is known about the biological roles of the TNFRSF19 in lung tissues." (PMID 31126313, 2019). "It was reported that β-catenin regulates TNFRSF19 expression in colorectal cancer cells." (PMID 39310276, 2024). "TNFRSF19, a member of the TNFR superfamily, is associated with increased susceptibility to nasopharyngeal cancer and has been found at elevated levels in various invasive cancers, including colorectal cancer, lung cancer, melanoma, and GBM." (PMID 38560169, 2024). "In another study using colorectal cancer cells, TNFRSF19 was identified as target gene downstream of the Wnt/β-catenin pathway and TNFRSF19 ligands activated NF-κB signaling, thus revealing an indirect way by which β-catenin positively regulates NF-κB activity." (PMID 27713747, 2016). "In addition, it has been shown that TNFRSF19 may be involved in the dysregulation of β-catenin activity that can result in the development of colorectal cancers." (PMID 33437203, 2021).
nasopharyngeal carcinoma (7 papers, 2019 to 2023). A carcinoma arising from the nasopharyngeal epithelium. "Further, TNFRSF19, essential for cell proliferation and development of nasopharyngeal carcinoma, represented a mechanism for tumor cells to escape from TGF-β growth-inhibitory action." (PMID 36437961, 2022).
lung carcinoma (6 papers, 2017 to 2024). "In a study on the association between TNFRSF19 expression and lung cancer risk, it has been found that the differentiated expression of TNFRSF19 is statistically significantly associated with tumor TNM stage and patient survival." (PMID 38250608, 2024). "In view of the potential clinical significance of TNFRSF19, the lung cancer suppressor function of TNFRSF19 and the underlying mechanisms are worthy of further investigation in vitro and in vivo." (PMID 31126313, 2019). "The SNP rs753955 was located in the intron at 13q12.12 region between MIPEP and TNFRSF19 identified as a risk locus of lung cancer by recent GWA studies." (PMID 28903315, 2017). "We further experimentally tested the tumor suppressor function of TNFRSF19 by transfecting A549 lung cancer cells that express a low level of this protein with TNFRSF19-expressing lentivirus vectors." (PMID 31126313, 2019). "Third, TNFRSF19 expression levels were significantly reduced in lung cancer tissues when compared with the para-cancer tissues." (PMID 31126313, 2019). "Differentiated expression of TNFRSF19 and its statistical significant correlation with tumor TNM staging and patient survival indicate a suppressor role of TNFRSF19 in lung cancer." (PMID 31126313, 2019). "The TNFRSF19 expression was significantly lower in lung cancer tissues than in the para-cancer tissues, in agreement with the data from the TCGA, Oncomine, and GEPIA databases." (PMID 31126313, 2019). "The survival analysis of 1145 lung cancer patients for more than 200 months showed the survival time was significantly longer for patients with high expression of TNFRSF19 than with low expression (p = 1.8e−09, log-rank test)." (PMID 31126313, 2019). "The observations that the TNFRSF19 expression was inversely correlated with tumor staging and positively correlated with patient survival time strongly suggest TNFRSF19 functions as a lung cancer suppressor." (PMID 31126313, 2019). "Second, the introduction of TNFRSF19 into A549 lung cancer cells dramatically suppressed malignant phenotypes of the cells, including soft agar colony formation and invasive ability." (PMID 31126313, 2019). "The evidence provided by our present study clearly points to TNFRSF19 as a lung cancer suppressor." (PMID 31126313, 2019). "Fourth, the TNFRSF19 expression levels were inversely correlated with the tumor staging and survival time, as revealed by our clinical sample analysis of 117 lung cancer patients and Kaplan-Meier analysis of 1145 lung cancer cases." (PMID 31126313, 2019). "We also evaluated the relationship between the TNFRSF19 expression levels and the TNM stages in the 117 lung cancer patients." (PMID 31126313, 2019).
melanoma (6 papers, 2008 to 2024). A malignant, usually aggressive tumor composed of atypical, neoplastic melanocytes. "TROY, called also TAJ or TNFRSF19, is a gene encoding an orphan member of the tumor necrosis factor (TNF) receptor superfamily that is implicated in several cancers, including melanoma and can promote Akt pathway." (PMID 32867069, 2020). "On the other hand, the upregulation of TNFRSF19 may suggest that a caspase independent cell death may take place in these cells, as already shown for 293T cells and that this same gene might promote cell growth as reported for melanoma cells." (PMID 19087308, 2008).
hepatocellular carcinoma (2 papers, 2022 to 2024). A malignant tumor that arises from hepatocytes. "In hepatocellular carcinoma studies, TNFRSF19 is involved in reshaping the tumor microenvironment, mediating immune evasion." (PMID 38644411, 2024).
acute kidney injury (1 paper, 2021). Sudden and sustained deterioration of the kidney function characterized by decreased glomerular filtration rate, increased serum creatinine or oliguria. "TNFα and TNFRSF19: The pathogenic role of TNFα is observed in models of immune-complex-mediated glomerulonephritis, lupus nephritis, Antineutrophil Cytoplasmic Antibody (ANCA)-associated glomerulonephritis, DN, Acute Kidney Injury (AKI), and kidney allograft rejection." (PMID 34576149, 2021).
colon carcinoma (1 paper, 2021). "The search for activators of NF-κB signaling in the SI will thus continue in the future, but Tnfrsf19 is a potential candidate as it is expressed in SI crypts, is regulated by Wnt in Lgr5-positive CBCs and appears to modulate Wnt signaling in human colon carcinoma cell lines." (PMID 34751748, 2021).
coronary artery disease (1 paper, 2024). "Previous studies have linked TNFRSF19 elevated expression to both intracranial aneurysms and coronary artery disease." (PMID 39596356, 2024).
Crohn disease (1 paper, 2025). A gastrointestinal disorder characterized by chronic inflammation involving all layers of the intestinal wall, noncaseating granulomas affecting the intestinal wall and regional lymph nodes, and transmural fibrosis. "For example, TLR7, NFKBIA, NFKBIZ, NFKB2, and TNFRSF19 have been shown to be upregulated in epithelial cells and macrophages during infection with AIEC strains isolated from Crohn’s disease patients." (PMID 40572318, 2025).
epilepsy (1 paper, 2013). A brain disorder characterized by episodes of abnormally increased neuronal discharge resulting in transient episodes of sensory or motor neurological dysfunction, or psychic dysfunction. "The other deletion carrier presenting with an additional genomic imbalance was the male proband referred for scalded-skin syndrome, who harboured an additional maternally inherited deletion at 13q12.12, encompassing the TNFRSF19 gene, in a region with reported linkage to epilepsy." (PMID 23637818, 2013).
leiomyoma (1 paper, 2023). A well-circumscribed benign smooth muscle neoplasm characterized by the presence of spindle cells with cigar-shaped nuclei, interlacing fascicles, and a whorled pattern. "For comparison of differential expression of genes in leiomyomas, there was a significant race/ethnicity correlation in expression for TNFRSF19, IRS4, PLEKHG4B, PGR, KRT17, CCDC177, MYO5B, and ZNF703." (PMID 37686244, 2023).
leukemia (1 paper, 2021). A malignant (clonal) hematologic disorder, involving hematopoietic stem cells and characterized by the presence of primitive or atypical myeloid or lymphoid cells in the bone marrow and the blood. "CD8 linker joined to CD8TM, CD4TM, TNFRSF19, TNFRSF16, and TNFRSF9 were then tested for surface expression and killing of CD19+ leukemia cell lines." (PMID 34893603, 2021).
lymphoma (1 paper, 2021). A malignant (clonal) proliferation of B- lymphocytes or T- lymphocytes which involves the lymph nodes, bone marrow and/or extranodal sites. "Here we develop an anti-CD19 CAR (CAR19) comprised of the 4-1BB co-stimulatory and TNFRSF19 transmembrane domains, showing anti-tumor efficacy in an in vivo xenograft lymphoma model." (PMID 34893603, 2021).
vascular dementia (1 paper, 2022). A degenerative vascular disorder affecting the brain. "In this context as well, FAM134B appears to have a strong synergistic epistasis with tumor necrosis factor receptor superfamily, member 19 (TNFRSF19) in the susceptibility to vascular dementia." (PMID 35188422, 2022).